TIGIT (T cell immunoreceptor with Ig and ITIM domains)
Diseases named in the same sentence as TIGIT in open-access papers (continued):
Sharing a sentence is not in itself a finding about the gene and the disease.
tumor (continued). "TIGIT down-regulate T cell and NK cell functions upon binding to its two ligands, CD155 and CD112, which are expressed by both tumor cells and antigen presenting cells." (PMID 36674809, 2023). "100% the of animals that had originally been cured were able to fully reject the subsequent tumor challenge, highlighting the generation of long-lasting curative antigen-specific CD8+ T cells following anti-TIGIT mAb treatment." (PMID 38022590, 2023). "The addition of TIGIT blockade to MWA resulted in the up-regulation of CXCL9 and CXCL10 expression in TAMs and their receptor CXCR3 expression in T cells, which restrain tumor growth and enhance anti-tumor immunity." (PMID 36900218, 2023). "On exhausted tumour-specific CD8+ T cell subsets, TIGIT co-expresses with other inhibitory receptors, LAG3 and TIM-3." (PMID 37325585, 2023). "The authors also demonstrated that tumor-infiltrating lymphocytes (TIL) expressed an immune receptor named T-cell immunoreceptor with Ig and ITIM domains (TIGIT), present on some T and NK cells which regulates T-cell-mediated immunity." (PMID 37764202, 2023). "Here we show, by analysing lymphocytes from matched human tumour and peripheral blood samples, that TIGIT and CD226 co-expression is rare on tumour-infiltrating lymphocytes." (PMID 37596248, 2023). "In contrast, all mIgG2a anti-TIGIT mAbs with intact FcγR binding (WT-TGT, SEA-TGT, and DLE-TGT) showed significant tumor growth delay in many of the disparate syngeneic models assessed." (PMID 38022590, 2023). "The results of this study demonstrated that OAd-SIRPα-Fc, OAd-Siglec10-Fc and OAd-TIGIT-Fc were able to produce SIRPα-Fc, Siglec10-Fc and TIGIT-Fc, respectively, which effectively bound to CD47+, CD24+ and CD155+ tumor cells." (PMID 38016957, 2023). "In the present investigation, while PDL1 and PDL2 expression in the tumor group was lower than that in the normal group, the expression of TIGIT, CTLA4, LAG3, and PD1 in the tumor group was higher than that in the normal group." (PMID 37266661, 2023). "Blockade of TIGIT and TIM-3 synergized to enhance antitumor immune responses in various mouse tumor models via Treg cells." (PMID 36829496, 2023). "One of the typical hallmarks of the tumor microenvironment is the up-regulation of inhibitory receptors including CTLA-4, TIM-3, PD1, LAG-3, and TIGIT on the surface of cytotoxic lymphocytes." (PMID 37629138, 2023). "TIGIT contains three ligands, of which PVR (CD155), expressed in tumor cells and APC, is the main ligand for TIGIT with high affinity." (PMID 36558902, 2022). "TIGIT binds to two ligands, CD155 (PVR) and CD112 (PVRL2, nectin-2), that are expressed by tumor cells and antigen-presenting cells in the tumor microenvironment." (PMID 35222404, 2022). "There is abundant evidence that, together with PD-L1, TIGIT and the subsequent activation of the TIGIT/CD155 axis are very effective in silencing immune responses to the tumor." (PMID 36551992, 2022). "Engagement of TIGIT to its ligands PVR and PVR-L2 leads to inhibitory signaling in T cells, promoting functional exhaustion of tumor-infiltrating T lymphocytes." (PMID 35273608, 2022). "F. nucleatum has also been shown to interact with the immune inhibitory receptors TIGIT and CEACAM1, thus protecting CRC cells from cytotoxicity by NK cells and tumour-infiltrating lymphocytes." (PMID 35301576, 2022). "The data revealed that the exhaustion status of CD8+ T cells was significantly improved in MPR tumor lesions, with reduced expression of exhausted markers, such as PDCD1, CTLA4, LAG3, and TIGIT." (PMID 35831283, 2022). "TIGIT competes with other members of the PVR-like family, CD96 and DNAM-1, for the binding of CD155 on tumor cells, where TIGIT binds to it with the highest affinity." (PMID 35327475, 2022). "A marked correlation between CD96/TIGIT messenger(m) RNA levels and CD3E/CD8a/CD4, with similar observations at the protein level (i.e., T cells), can be seen across multiple tumor types." (PMID 35812451, 2022).
tumor (continued). "SIGLEC15, PDCD1LG2 (PD-L2), TIGIT, PDCD1 (PD-1), CD274 (PD-L1), CTLA4, LAG3, and HAVCR2 (TIM3) are transcripts related to immunological checkpoints that perform a vital function in tumor immune evasion." (PMID 36042287, 2022). "Meanwhile, the addition of TIGIT blockade to MWA prolonged survival and delayed tumor growth in the mouse MC38 tumor model." (PMID 35320940, 2022). "As expected, DEGs that were upregulated in T cells from tumor tissues, such as CTLA4 and TIGIT, were enriched for exhausted T cell functions." (PMID 36104333, 2022). "It competes with TIGIT for the CD155 receptor found on antigen-presenting cells, tumor cells and virus-infected cells." (PMID 36131131, 2022). "We showed that tumor-Ag-specific CD8 T cells at the tumor site, which expressed the ICs PD-1, TIGIT, CTLA-4, and TIM-3, as well as CD39, are at an advanced effector memory (CD45RA-CCR7-) differentiation stage and, for the most part, lose CD28 expression." (PMID 35954341, 2022). "Combined treatment with OX and TIGIT blockade fostered CD8+ T-cell infiltration into tumors and delayed tumor progression." (PMID 36389751, 2022). "Taken together, our findings showed that TIGIT blockade in combination with MWA significantly promoted the expansion and functions of CD8+ TILs and reshaped myeloid cells in the tumor microenvironment (TME) using flow cytometry and scRNA-seq analysis." (PMID 35320940, 2022). "In animal studies, while each individual inhibition does not significantly hamper the growth of CT26 tumors, the inhibition of TIGIT and PD-1/PD-L1 enhances the activity of anti-tumor CD8+ T cells and leads to a complete reduction in tumor size." (PMID 36231109, 2022). "Blocking the TIGIT/CD155 pathway improves CD8+ T cell effector function and slows tumour progression." (PMID 35729552, 2022). "Considering the complex regulation of NK cell responses, we will focus only on selected inhibitory receptors that are known to suppress NK cells functions in tumour, such as KIR2DL1–3, KIR3DL1–2, NKG2A/CD94, TIGIT, PD-1, LAG-3, and Tim-3." (PMID 35806034, 2022). "TIGIT’s receptor, CD155, is highly expressed on DCs, fibroblasts, endothelial cells and tumor cells within the TME, creating a highly immunosuppressive environment." (PMID 35345849, 2022). "TIGIT can inhibit the NK cell-mediated immune response by binding to CD155, thereby suppressing the anti-tumor effect of CD8+T cells." (PMID 35433470, 2022). "We found that 47 genes were upregulated in tumor tissues compared to normal tissues, such as CD48, TIGIT, GNLY, CCL19, CCL5, CXCL13, CCL17 and NKG7." (PMID 36713530, 2022). "TIGIT binds to two ligands, CD155 and CD112, that are expressed by tumor cells and APCs to down-regulate T cell and NK cell functions." (PMID 35053435, 2022). "TIGIT binds to two ligands (CD155 and CD112) that are expressed by tumor cells and antigen-presenting cells in the tumor microenvironment." (PMID 36568253, 2022). "These include T-cell immunoglobulin and ITIM domain (TIGIT) and Programmed Cell Death Protein 1 (PD-1) and their ligands, CD155 and PDL-1/2 in virus-infected and tumor cells." (PMID 35887206, 2022). "They found that, in comparison with the immune cell population of tumor-free lungs (TFL), MPM TILs had a much higher number of Tregs (2.2% vs. 12.8% of CD4+ population, respectively), and that these highly expressed TIGIT (72.5% of cells)." (PMID 35327475, 2022). "Significant expressions of co-inhibitory receptors including PDCD-1, TIGIT and TIM3 were identified in immune cells, and other tumor immunity-related genes were also highly expressed." (PMID 36148946, 2022). "A recent review stated that the main immune checkpoints on tumor-infiltrating and peripheral Tregs are CTLA-4, PD-1/PD-L1, LAG-3, TIM-3 and TIGIT." (PMID 36009853, 2022). "Animal models and clinical studies have shown that Tim-3, TIGIT, LAG-3, PD-1, and PD-L1 targeted therapies have promising effects in enhancing antitumor immunity in a wide variety of tumor types." (PMID 35318258, 2022).
tumor (continued). "We observed significantly higher levels of exhaustion (ICOS, TIM3, CTLA4, PD1, LAG3, TIGIT) and activation (TNFSR9, CD69, CD25) markers for clonotypes restricted to the tumor." (PMID 36185254, 2022). "A recent study reported, using flow cytometry analysis, the expression, in descending order, of TIGIT, PD-1 and Tim-3 by the TILs (CD4+ and CD8+) of CRC (and that of their ligands by tumor cells)." (PMID 36077799, 2022). "In the tumor microenvironment, infiltrating immune cells experience functional impairment by expressing multiple inhibitory signals on the cell surface, such as PD-1/PD-L1, CTLA-4, TIGIT, and TIM-3, leading to tumor immunosuppression." (PMID 35844572, 2022). "TIGIT shows higher affinity to CD155, which is expressed on dendritic cells and tumor cells, than the immune-activating receptor CD226 (also known as DNAM1) on the cytotoxic T cells and NK cells, resulting in suppression of immune activation." (PMID 35572593, 2022). "In a second phase, they used an antibody directed against TIGIT in mice with HNSCC and observed a deceleration of tumor progress, which seemed to be mostly dependent on CD8+ T cell regeneration." (PMID 36551992, 2022). "Chronic antigen stimulation is known to produce up-regulation of PD-L1/PDL-2 on tumor cells and expression of exhaustion markers, such as PD-1, TIM-3, LAG-3, and TIGIT on T-lymphocytes, which hamper immune response." (PMID 35740552, 2022). "Specifically, activated Treg cells destroy tumour immunity by enriching a series of costimulatory molecules (such as ICOS, CD27, 41BB, OX40, and GITR) and immune checkpoints (PD-1, CTLA-4, LAG3, and TIGIT) to promote tumour immune evasion." (PMID 36110969, 2022). "We detected higher percentages of CXCL16+ DCs in the MWA plus TIGIT group compared with the MWA group, indicating that the combination of TIGIT blockade and MWA induced immunoreactivity and enhanced tumor control." (PMID 35320940, 2022). "After analyzing the tumor infiltrating CD8+ T cells, we found significant reductions of PD1, CD39, and TIGIT levels in Cd47−/− mice." (PMID 36105746, 2022). "Our observation of increased frequency of Tregs with an activated phenotype combined with dysfunctional TIGIT‐expressing CD4 and CD8 T cells suggests dampening of anti‐tumor T‐cell responses in lymph nodes with established metastases." (PMID 34165864, 2022). "In the tumor infiltrate, T cells and NK cells are affected by AIF1, which promotes TIGIT expression, and hence induces or strengthens immunotherapy resistance sustained by an immune infiltrate enriched in Th1 cells and exhausted T cells." (PMID 35656508, 2022). "TIGIT+ Treg-infiltrating tumors have been found to be characterized by an upregulation of TIM-3, and inhibiting TIM-3 in Tigit−/− mice further reduces tumor size and increases overall survival." (PMID 36231109, 2022). "This study combines a novel strategy of radiotherapy that utilizes high- and low- dose radiation with immune oncology agents (anti-TIGIT and anti-PD1 monoclonal antibodies) in order to overcome the inhibitory tumor stroma and battle tumors systemically." (PMID 35008385, 2022). "A potentially important signaling pathway that is involved in regulating anti-tumor immunity is the T cell immunoreceptor with Ig and ITIM domains (TIGIT)-CD96-CD226 axis." (PMID 36140247, 2022). "When CD155 is up-regulated in tumor cells, co-stimulatory molecule DNAM-1 recognizes and binds to tumor cells to stimulate immunity, while the inhibitory receptor TIGIT induces intracellular signaling to exert inhibitory effects." (PMID 36309698, 2022). "Consistently, blockade of the NKG2A or TIGIT axes promotes both NK and CD8+ T cell effector functions and potentiates the anti-tumor immune response." (PMID 35887206, 2022). "Alongside TNFRSF4/OX40 and TNFRSF9/4-1BB, we selected a number of markers of tumor-resident Tregs (CTLA4, ICOS, TIGIT, and FOXP3) and performed k-means clustering for all UPS, MFS, and DDLS samples in the TCGA." (PMID 35558159, 2022).
tumor (continued). "Co-transduction of a TIGIT : CD28 CSR together with a tumor-specific TCR or CAR into human T-cells, drove enhanced cytokine production and superior anti-tumor function in a xenograft model of established human melanoma tumors." (PMID 35432319, 2022). "Unexpectedly, a high level of SPINK1 expression was found to be significantly and positively correlated with the high expressions of PD-1, LAG-3, TIM-3, TIGIT, and CTLA-4 in the tumor samples from the TCGA cohort." (PMID 35924241, 2022). "The expression of TIGIT in BC is related to highly aggressive subtypes, including basal-like BC subtype, triple negative BC, and HER2 positive BC or higher-grade tumor." (PMID 36497240, 2022). "The importance of CD226 in regulating anti-tumor responses is demonstrated in mouse tumor models where use of a CD226-neutralizing monoclonal antibody (mAb) abrogates the efficacy of combining mAbs against PD-L1 and TIGIT." (PMID 35263569, 2022). "The main ligand for TIGIT is CD155, which is upregulated on cancer cells and is also expressed on tumour-infiltrating myeloid cells." (PMID 36297474, 2022). "The combination therapy of the TIGIT mAb and CD226 agonist further activated NK cells and produced a greater anti-tumor response." (PMID 36303184, 2022). "Abundant studies have suggested that Foxp3 regulates the expression of several genes (CTLA-4, PD-1, LAG-3, TIM-3, TIGIT, TNFR2) involved in carcinogenesis to utilize its tumor suppressor function through knockout models." (PMID 36009853, 2022). "Following T cells and NK cells upregulate TIGIT expression, which leads to an immunosuppressive TME, promoting tumor progression, immune escape, and metastases that result in poor prognosis." (PMID 35656508, 2022). "At the cellular level, scRNA-seq and CyTOF of NSCLC patients revealed that while PD-1 and TIGIT were expressed throughout the CD8+ T cell compartment, CD226 and CD28 were co-expressed by distinct populations likely important for tumor immunity." (PMID 35263569, 2022). "TIGIT binds to two ligands, CD155 (PVR) and CD112 (PVRL2, nectin-2), which are expressed by tumour cells and antigen-presenting cells in the tumour microenvironment." (PMID 35057760, 2022). "CTLA4, HAVCR2, PVRL2, PDCD1, SIGLEC15, TIGIT, and VTCN1 expression levels were higher in tumor tissues, while CD244, LAG3, PDCD1LG2, and CD274 expression levels were found to be lower." (PMID 35923695, 2022). "According to a recent study, gastric cancer cells suppress CD8 T-cell metabolism via CD155/TIGIT signaling, which blocks CD8 T-cell effector activities, leading to hyporesponsive anti-tumor immune reaction." (PMID 35999569, 2022). "NECTIN1 and NECTIN4 are most strongly expressed in tumor cells, but NECTIN2 and NECTIN3 are also expressed in some lymphocyte cell types, while TIGIT is largely expressed in Tregs and exhausted CD4+ T cells." (PMID 35995947, 2022). "TASCs, DC_LAMP3, and tumor cells, all highly expressed NECTIN2 and PVR (CD155), whose interaction with TIGIT blocks T-cell activation and proliferation." (PMID 35999201, 2022). "Of note, TIGIT expression was limited to the CD44+ memory subset and the expression level increased over time during tumor development." (PMID 36569934, 2022). "Multiplexed analysis of tumour cells showed that FAK regulates the expression of CD155, a checkpoint ligand for TIGIT (T cell immunoreceptor with immunoglobulin and immunoreceptor tyrosine-based inhibitory motif domains)." (PMID 35929603, 2022). "Their results indicate that the expression of TIM-3 and also TIGIT, PD-1, CD39 on Vδ1 cells differs among PBLs, MALs and TILs (tumor-infiltrating lymphocytes) in patients with OC and is dependent on interactions with the tumor microenvironment." (PMID 36359346, 2022). "The interaction between TIGIT and CD155 can mediate the functional exhaustion and hyporesponsiveness of lymphocytes, and induce the immune escape of tumor cells." (PMID 35433470, 2022).